PAX1 (paired box 1)
Description:
This protein is a transcriptional activator. It may play a role in the formation of segmented structures of the embryo. May play an important role in the normal development of the vertebral column (By similarity).
Synonyms: HUP48; OFC2; OTFCS2
Tractability: PROTAC: ubiquitination databases record sites on it.
Gene: Protein-coding gene on chromosome 20 (21,705,659 to 21,718,481, forward strand). Ensembl gene ENSG00000125813.
Subcellular location: Nucleus
Gene Ontology:
Molecular function: sequence-specific double-stranded DNA binding; DNA-binding transcription factor activity, RNA polymerase II-specific; RNA polymerase II cis-regulatory region sequence-specific DNA binding; DNA binding
Biological process: embryo development ending in birth or egg hatching; regulation of transcription by RNA polymerase II; skeletal system development; transcription by RNA polymerase II; regulation of DNA-templated transcription
Cellular component: chromatin; nucleus
Genetic constraint (gnomAD): Loss-of-function variants: 18 observed, 31.04 expected, observed/expected ratio (o/e) 0.58, 90% interval 0.4 to 0.86. The synonymous counts are far from expectation, so gnomAD's model fits this gene poorly and the ratio says little. Missense variants: 760 observed, 611.28 expected, observed/expected ratio (o/e) 1.24, 90% interval 1.17 to 1.32. Synonymous variants: 397 observed, 287.53 expected, observed/expected ratio (o/e) 1.38, 90% interval 1.27 to 1.5.
Gene-disease validity (ClinGen):
ClinGen rates the evidence that PAX1 causes each of these diseases.
otofaciocervical syndrome 2 (autosomal recessive): Definitive. Any otofaciocervical syndrome in which the cause of the disease is a mutation in the PAX1 gene.
Homologues: Orthologues: chimpanzee PAX1 (99% identical), macaque PAX1 (93% identical), pig PAX1 (92% identical), dog PAX1 (90% identical), mouse Pax1 (89% identical), rat Pax1 (89% identical), rabbit PAX1 (84% identical), guinea pig PAX1 (79% identical), tropical clawed frog pax1 (59% identical), zebrafish pax1a (57% identical), zebrafish pax1b (52% identical), Drosophila melanogaster Poxm (34% identical). Paralogues in human: PAX9 (48% identical), PAX2 (30% identical), PAX7 (30% identical), PAX5 (30% identical), PAX8 (30% identical), PAX3 (29% identical), PAX4 (21% identical), PAX6 (11% identical), EVX2 (9% identical), VSX2 (9% identical), DUX4 (9% identical), ALX3 (8% identical), and 38 more.
Diseases named in the same sentence as PAX1 in open-access papers:
PAX1 is named in the same sentence as 74 diseases in open-access papers, as found by Europe PMC text mining. Sharing a sentence is not in itself a finding about the gene and the disease. The quoted sentences say what the papers report.
cervical cancer (36 papers, 2012 to 2026). A primary or metastatic malignant neoplasm involving the cervix. "The methylation status of the PAX1 gene is associated with the development of various cancers, including cervical cancer." (PMID 40291776, 2025). "This study confirms the high diagnostic performance of PAX1 methylation in cervical cancer screening." (PMID 41229153, 2025). "HR-HPV infection, MTHFR polymorphism, and DNA methylation of PAX1 are all risk factors for cervical cancer." (PMID 40291776, 2025). "Previous studies have demonstrated that PAX1 gene methylation offers valuable diagnostic potential for cervical cancer." (PMID 41229153, 2025). "The findings indicate that HR-HPV infection, MTHFR polymorphism, and PAX1 methylation increase the risk of cervical cancer and its precursors, with MTHFR polymorphism and PAX1 methylation showing an additive interaction effect on cervical lesion development." (PMID 40291776, 2025). "To further assess the diagnostic performance of PAX1 methylation in cervical cancer, we conducted a comprehensive meta-analysis of studies published up to 1 September 2022." (PMID 41229153, 2025). "PAX1 methylation demonstrates high diagnostic accuracy for cervical cancer and is a promising noninvasive biomarker for screening and triage." (PMID 41229153, 2025). "It has been suggested that PAX1 methylation is associated with HPV16/18 infection in cervical cancer, which further influences the efficacy of radiotherapy by inducing the methylation of the PAX1 promoter in host cells." (PMID 38651153, 2024). "We studied the potential mechanism of PAX1 causing radioresistance in cervical cancer cells by transcriptome analysis." (PMID 37533109, 2023). "first reported that abnormal methylation of PAX1 was associated with cervical cancer, and that the PAX1 gene was found to be silenced by hyper-methylation and under-expressed in cervical cancer biopsies." (PMID 36713512, 2022). "Specifically, we characterized aberrantly methylated host promoter genes (RARB, CADM1, DAPK1, and PAX1) and their possible association with: invasive cervical cancer, cervical cancer stage, HIV status, age, high-risk HPV genotypes." (PMID 33718129, 2021). "This review summarizes reports of PAX1 methylation and its promising role in cancer screening, especially that associated with cervical cancer." (PMID 30636379, 2019). "Despite this diagnostic association with cervical cancer, however, there remains a gap in the mechanistic understanding of the precise role of PAX1 in disease etiology." (PMID 31235851, 2019). "Diagnostic indices of PAX1 methylation for cervical cancer screening." (PMID 41229153, 2025). "Univariate and multivariate logistics regression analyses were performed to determine whether PAX1 methylation is an independent risk factor for poor prognosis in cervical cancer." (PMID 37533109, 2023). "In summary, PAX1 gene methylation status was a potential prognostic biomarker, our study innovatively studied the role of PAX1 in radioresistance and established a visual nomogram to predict the risk of residual tumor in patients with cervical cancer receiving radiotherapy." (PMID 37533109, 2023). "Studies have demonstrated that PAX1 methylation levels are closely associated with the severity of cervical lesions and may play a pivotal role in the initiation and progression of cervical cancer." (PMID 40777030, 2025). "Furthermore, hypermethylated PAX1 associated with poor prognosis in cervical cancer." (PMID 31235851, 2019). "The tumor suppressor paired box gene 1 (PAX1) was reported to present abnormal methylation in cervical cancer, and its methylation increased with disease grade, indicating the potential of PAX1 methylation as a biomarker for cervical cancer screening." (PMID 40291776, 2025). "The presence of additive interaction, particularly in the context of CIN II/III and cervical cancer progression, underscores the heightened risk conferred when both MTHFR polymorphisms and PAX1 methylation are present." (PMID 40291776, 2025).
cervical cancer (continued). "Our conditional and clustering analyses demonstrated that the addition of NREP‐AS1 methylation appears to independently improve the overall accuracy of PAX1 for the detection of cervical cancer." (PMID 40065506, 2025). "In 2016, the Taiwan Food and Drug Administration approved PAX1 methylation as an adjunct to cytological testing for cervical cancer screening." (PMID 40564169, 2025). "In conclusion, the results indicate that HR-HPV infection, MTHFR mutations, and PAX1 methylation increase the risk of CIN and cervical cancer." (PMID 40291776, 2025). "This study supports the clinical utility of PAX1 methylation as a promising biomarker for cervical cancer screening." (PMID 41229153, 2025). "This suggests that PAX1 methylation performs particularly well in identifying cervical cancer, although it is less effective in detecting HSIL." (PMID 41229153, 2025). "Various types of DNA methylation, such as those involving PAX1, ZNF582, and FAM19A4, are strongly linked to CINs and cervical cancer." (PMID 40291776, 2025). "In this study, we explored the roles and interactions of HR-HPV infection, MTHFR polymorphism, and PAX1 methylation in CIN and cervical cancer." (PMID 40291776, 2025). "In cervical cancer, the PAX1 gene, which acts as a tumor suppressor, is silenced through methylation." (PMID 40291776, 2025). "The present study provided compelling evidence of the interaction between MTHFR polymorphisms and PAX1 methylation on the progression of cervical lesions, specifically CIN II/III and cervical cancer." (PMID 40291776, 2025). "In particular, PAX1 methylation has shown promising sensitivity and specificity as a biomarker in cervical cancer." (PMID 41229153, 2025). "In recent years, multiple studies have reported promising results for PAX1 methylation as a biomarker in cervical cancer screening." (PMID 41229153, 2025). "Through multivariate logistics regression analysis, a nomogram based on PAX1 methylation for predicting the radiotherapy sensitivity of patients with cervical cancer was constructed by R software." (PMID 37533109, 2023). "In this study, we detected the status of PAX1 methylation of tumor exfoliated cells from patients with cervical cancer before concurrent chemo-radiotherapy." (PMID 37533109, 2023). "In the market, there are also two CE-marked tests for the detection of cervical cancer (Cervi-M®) and oral cancer (Oral-M®) by analyzing PAX1 and ZNF582 gene methylation in cervix smears and oral epithelial cells." (PMID 37511475, 2023). "PAX1 is a tumor suppressor gene, and high PAX1methylation levels induce tumorigenesis, such as cervical cancer." (PMID 36678411, 2022). "We found that if the △Cp PAX1 cut-off value is lower than 6.360, it is highly suggestive of invasive cervical cancer." (PMID 36713512, 2022). "Paired PAX1 methylation was found to be a valuable biomarker for cervical cancer screening, a commonly used method in our hospital, with a 77% sensitivity and 92% specificity of CIN3+ versus normal." (PMID 37551167, 2022). "Here, we evaluated the predictive value of PAX1 methylation in concurrent chemo-radiotherapy (CCRT) outcomes in cervical cancer." (PMID 34335930, 2021). "Our data further confirm the possible role of promoter methylation of RARB, CADM1, DAPK1, and PAX1 in cervical cancer tumorigenesis." (PMID 33718129, 2021). "The progression of cervical cancer is dependent on multiple tumor suppressors including PAX1, SOX1, LMX1A and ZNF5826-8." (PMID 34335930, 2021). "We analyzed the methylation level of PAX1 gene in cervical cancer cells during different periods of CCRT using qMSP-PCR and found that PAX1 methylation level can predict and monitor early therapeutic response." (PMID 34335930, 2021).
cervical cancer (continued). "In currently, aberrant methylation of PAX1 is found in variety of solid tumors, including cervical cancer." (PMID 34335930, 2021). "Our result indicates that PAX1 methylation as a promising biomarker plays an important role in monitoring and treatment following up of cervical cancer." (PMID 34335930, 2021). "In this study, we investigated the predictive value of PAX1 methylation status in monitoring the early response to radiotherapy in cervical cancer." (PMID 34335930, 2021). "In further studies, it will be essential to analyze the correlation between SOX1 and PAX1 methylation status and sensitivity of the cervical cancer cell to radiotherapy and chemotherapy." (PMID 33376722, 2020). "Our previous studies reported PAX1 as hypermethylated in cervical cancer tissues, thereby suggesting it as a potential screening marker." (PMID 30636379, 2019). "According to current evidence, combined testing for human papillomavirus and PAX1 methylation analysis represents an efficacious cervical cancer‐screening protocol." (PMID 30636379, 2019). "PAX1 methylation represents a novel biomarker that exhibits increased specific and accuracy for cervical cancer screening and diagnosis." (PMID 30636379, 2019). "To understand further the status of PAX1 promoter methylation in cervical cancers, we extracted and analyzed DNA methylation profiles from a TCGA dataset." (PMID 31235851, 2019). "Aside from cervical cancer, PAX1 also displays hypermethylation in other tumors and offers great promise as a marker for cancer detection." (PMID 30636379, 2019). "In a study that evaluated the effect of nutraceuticals, including resveratrol, on the inhibition of cervical cancer through the reactivation of PAX1, it was reported that resveratrol was capable of reactivating PAX1 expression in Caski cells." (PMID 30781847, 2019). "In 2016, the Taiwanese FDA approved the application of PAX1 methylation as an adjunct of conventional cytology in cervical cancer screening." (PMID 31235851, 2019). "Meta‐analyses also supported the utility of PAX1 methylation as an auxiliary biomarker in cervical cancer screening." (PMID 30636379, 2019). "The efficacy of PAX1 methylation testing in detecting cervical cancer is significantly improved with a combination of cervical cell cytology or HPV 16, 18 genotyping." (PMID 28241446, 2017). "The findings collectively suggested that PAX1 methylation and MTHFR polymorphism might have an interaction effect on the occurrence and progression of cervical cancer." (PMID 40291776, 2025). "We aimed to investigate the roles and interaction effects of high-risk human papillomavirus (HR-HPV) infection, methyltetrahydrofolate reductase (MTHFR) polymorphism, and paired box gene 1 (PAX1) methylation in cervical intraepithelial neoplasia (CIN) and cervical cancer." (PMID 40291776, 2025). "A DOR greater than 1 suggests that PAX1 methylation is a strong discriminator for cervical cancer." (PMID 41229153, 2025). "Future research could further expand the scope to explore the application value of PAX1 gene or other gene methylation detection in the comprehensive management of cervical cancer." (PMID 40777030, 2025). "As a bigenic methylation marker, PAX1/NREP‐AS1 (cg16767801 + cg23642047) was able to detect CIN3 or invasive cervical cancer with a sensitivity of 83%, specificity of 87%, and an AUC of 0.92 in a validation set, with a good predictive performance for CIN3 in an independent replication set." (PMID 40065506, 2025). "Our results revealed that radiotherapy response of patients with cervical cancer could be attributed to PAX1 methylation status; hypomethylated PAX1 correlated with an increasing incidence of radiation resistance in patients with cervical cancer." (PMID 37533109, 2023). "The present study demonstrated that PAX1 hypomethylation could be used as a promising biomarker to predict radioresistance in cervical cancer." (PMID 37533109, 2023).
cervical cancer (continued). "PAX1 gene methylation plays an important role in the development of cervical cancer." (PMID 37533109, 2023). "Clinically, most PAX1 methylation studies initially focused on the screening of cervical cancer." (PMID 37533109, 2023). "To clarify the mechanism of PAX1 methylation involved in radioresistance in cervical cancer, we overexpressed PAX1 gene in cervical cancer cell lines, and we found that cervical cancer cells overexpressing PAX1 had a higher survival rate after 6 Gy of radiation exposure." (PMID 37533109, 2023). "PAX1 hypomethylation status could be used as a promising biomarker to predict radioresistance in cervical cancer." (PMID 37533109, 2023). "An increasing number of studies have confirmed PAX1 methylation as a promising biomarker for cervical cancer based on its ability to discriminate between high‐grade cervical lesions and normal tissues, resulting in a reduced necessity for colposcopy referral and biopsy." (PMID 36713512, 2022). "In the last decade, a growing body of evidence has implied an emerging tumor suppressing role of PAX1 in various human cancers, including cervical cancer, ovarian cancer, colorectal carcinoma, parathyroid tumor, as well as oral squamous cell carcinoma, and so on." (PMID 36393845, 2022). "PAX1 can regulate cell division and differentiation, and methylation and silencing of PAX1 is closely related to the progression of precancerous lesions into cervical cancer." (PMID 36713512, 2022). "In addition, the role of PAX1 gene methylation in cervical cancer and precancerous lesions screening has been confirmed in previous study." (PMID 34335930, 2021). "In present study, we detected 83% methylation rate of PAX1 in the cervical cancer tissues." (PMID 34335930, 2021). "Therefore, our study aimed to characterize methylation status of four host genes (RARB, CADM1, DAPK1, and PAX1) that have been studied to a great extent in relation to cervical cancer." (PMID 33718129, 2021). "In conclusion, we found that PAX1 gene methylation status will change under the influence of radiation, and may predict early treatment response of cervical cancer patients post-radiotherapy." (PMID 34335930, 2021). "The role of PAX1 gene detecting in cervical cancer screening and triage has been demonstrated." (PMID 34335930, 2021). "In addition, this study further substantiated the previous studies results of overall high frequency of methylation rate in promoter regions of RARB, CADM1, DAPK1, and PAX1 genes in cervical cancer subjects." (PMID 33718129, 2021). "Therefore, PAX1 methylation level is a promising biomarker for cervical cancer screening and early diagnosis." (PMID 34335930, 2021). "Early decrease of PAX1 level indicates a better response to radiotherapy and a favorable prognosis in cervical cancer, whereas minute fluctuations may reflect a therapeutically unresponsive tumor." (PMID 34335930, 2021). "Additionally, 15 individual studies showed that single PAX1 methylation allowed the accurate differential diagnosis of cervical cancer/HSIL patients from normal individuals with a sensitivity of 0.80 and a specificity of 0.89." (PMID 30636379, 2019). "Similar results showed that curcumin, resveratrol, and DNMT1 influence PAX1 activity and might represent effective targets for treatment of cervical cancer (Parashar, Parashar, & Capalash, 2017)." (PMID 30636379, 2019). "However, additional standardization and large‐scale clinical studies are needed to evaluate the efficacy of PAX1 methylation for cervical cancer screening and early detection." (PMID 30636379, 2019). "Numerous studies have demonstrated that PAX1 methylation plays an important role in the progression of cancers and contributes significantly to the sensitivity and specificity of cancer screening, especially for cervical cancer." (PMID 30636379, 2019).